CSN2 (casein beta)
Description:
Important role in determination of the surface properties of the casein micelles.
Synonyms: CASB; PDC213
Tractability: Antibody: its Gene Ontology location is reachable by antibodies, with high confidence; UniProt places it where antibodies can reach, with medium confidence; UniProt predicts a signal peptide or a membrane-spanning region.
Gene: Protein-coding gene on chromosome 4 (69,955,256 to 69,965,728, reverse strand). Ensembl gene ENSG00000135222.
Subcellular location: Secreted
Pathways (Reactome):
Developmental Biology: Developmental Lineage of Mammary Gland Alveolar Cells
Signal Transduction: Nuclear signaling by ERBB4
Gene Ontology:
Molecular function: cysteine-type endopeptidase inhibitor activity; protein binding; calcium ion binding; enzyme inhibitor activity
Biological process: lactation; calcium ion transport
Cellular component: extracellular region
Genetic constraint (gnomAD): Loss-of-function variants: 11 observed, 15.59 expected, observed/expected ratio (o/e) 0.71, 90% interval 0.44 to 1.17. The upper end of that interval is the gene's LOEUF score, 1.17, which puts it in group 5 of 6, group 1 being the genes least tolerant of losing a copy. Missense variants: 281 observed, 236.5 expected, observed/expected ratio (o/e) 1.19, 90% interval 1.08 to 1.31. Synonymous variants: 114 observed, 89.94 expected, observed/expected ratio (o/e) 1.27, 90% interval 1.09 to 1.48.
Homologues: Orthologues: chimpanzee CSN2 (98% identical), macaque CSN2 (91% identical), dog CSN2 (66% identical), pig CSN2 (62% identical), rabbit CSN2 (52% identical), mouse Csn2 (47% identical), rat Csn2 (45% identical).
Diseases named in the same sentence as CSN2 in open-access papers:
CSN2 is named in the same sentence as 14 diseases in open-access papers, as found by Europe PMC text mining. Sharing a sentence is not in itself a finding about the gene and the disease. The quoted sentences say what the papers report.
breast carcinoma (4 papers, 2010 to 2025). "Genes that showed a positive correlation with Csn2 only during tumourigenesis included a number of factors that are associated with basal-like breast cancer, among them a master regulator of alveologenesis Cebpb8." (PMID 33686070, 2021). "This is in contrast to the recent report that TNFα stabilized Snail through NF-κB-dependent induction of CSN2 in breast cancer cells, which inhibited the association of Snail with GSK3β and thus suppressed its phosphorylation and degradation." (PMID 20661477, 2010). "However, the molecular evidence remains limited regarding how these genes contribute to breast cancer initiation and progression, highlighting the need for further investigation into both CSN1S1and CSN2 as potential prognostic markers." (PMID 40986521, 2025).
mastitis (3 papers, 2009 to 2022). Inflammation of breast tissue during lactation or postpartum due to an obstructed duct or infection. "Research has found that subclinical mastitis affected protein composition of milk, and LPS-induced mastitis affected the expression of milk protein genes (Csn1s1 and Csn2)." (PMID 33505589, 2021). "The decrease in milk production during mastitis in dairy cows is due to pathogens (such as S. aureus and Escherichia coli) that induce hypoxia, oxidative stress, and apoptosis, while suppressing the expression of milk genes (Csn2, Lalba, and Csn1s1) in the mammary gland." (PMID 35795861, 2022).
colon cancer (2 papers, 2016 to 2025). "Taken together, these results indicate that DDA1 promotes the progression of stage IIB–IIC colon cancers by activating the NFκB/CSN2/GSK-3β pathway." (PMID 26942699, 2016). "In summary, DDA1 promotes the progression of stage II colon cancer through the activation of the NFκB/CSN2/GSK3β pathway." (PMID 26942699, 2016). "Mechanistically, we found that DDA1 promoted proliferation and invasion in colon cancer cells by enhancing and stabilizing p-IKKβ and triggering the phosphorylation and degradation of IκBα followed by the activation of NFκB/CSN2/GSK3β signaling." (PMID 26942699, 2016). "Moreover, colon cancer progression is influenced by the SIRT2 through its regulation of NF-κB and CSN2, triggering the NF-κB/CSN2 signaling axis that induces Snail expression and enhances metastatic potential." (PMID 41428704, 2025).
colorectal cancer (2 papers, 2018 to 2022). A primary or metastatic malignant neoplasm that affects the colon or rectum. "While CSN2 has been shown to regulate SNAIL stability through inhibiting its phosphorylation by GSK-3β, CSN6 has been shown to be overexpressed in colorectal cancer and involved in its development." (PMID 29755680, 2018).
allergic reactions (1 paper, 2019). "These loci were localized at the beginning of the coding region of two genes encoding for the proteins CSN2 and PAEP, both present in cow milk and responsible for allergic reactions in humans." (PMID 31624292, 2019).
gastric cancer (1 paper, 2022). A primary or metastatic malignant neoplasm involving the stomach. "Serum CSN2 levels serve as a prognostic marker in gastric cancer, and low serum CSN2 is associated with poor survival in patients with gastric cancer." (PMID 35315259, 2022).
tumor (7 papers, 2015 to 2025). "We also demonstrated that DDA1-mediated tumor progression is associated with the activation of the NFκB/COP9 signalosome 2(CSN2)/glycogen synthase kinase3β (GSK3β) pathway." (PMID 26942699, 2016). "As one of the most conserved CSN subunits, CSN2 is involved in the proliferation and development of early embryos as well in anti-tumor activity as a tumor suppressor at low levels in mouse." (PMID 30863322, 2019). "As shown in, the nuclear localization of p65 (12 of 15 cases) and CSN2 (13 of 15 cases) in HCC tumor tissues (T) (red arrow) was higher than their para-tumor tissues (PT), which is highly consistent with the enhanced expression of RMP in these tissues." (PMID 28423737, 2017). "p65 nuclear translocation reportedly induces CSN2 upregulation followed by phosphorylation of GSK3β at serine 9, which promotes tumor metastasis and EMT." (PMID 26942699, 2016). "In addition, NFκB activation is required for the induction of the CSN2/GSK3β pathway, which enhances tumor invasion and metastasis." (PMID 26942699, 2016).
cancer (4 papers, 2017 to 2022). A tumor composed of atypical neoplastic, often pleomorphic cells that invade other tissues. "Csn2 was downregulated in muscles of Lewis lung carcinoma bearing rodents, a result that was later confirmed also for skeletal muscles in cancer patients." (PMID 33114658, 2020). "Intriguingly, Csn2 was among only nine proteins whose expression was normalized by exercise, a known non-pharmacological treatment to counter the cachexic effects of cancer therapy." (PMID 33114658, 2020). "Another study investigated a role for Csn2 (also known as Cops2) in a rodent cancer cachexia model." (PMID 33114658, 2020). "However, CSN2 has been found to inhibit the degradation of Snail in cancer cells." (PMID 35315259, 2022). "Therefore, clarifying the role of CSN2 in cancer is essential." (PMID 35315259, 2022). "Remarkably, our study demonstrates a mechanism of stabilizing Snail by NF-κB/CSN2 axis in the process of RMP-induced EMT and cancer metastasis." (PMID 28423737, 2017).
infection (3 papers, 2008 to 2025). The state of being infected such as from the introduction of a foreign agent such as serum, vaccine, antigenic substance or organism. "With respect to Jersey breed, peptides resulting from partial digestion of high abundant proteins such as LALBA, CSN2 and CSN3 in the small intestine may influence gut functions including immune stimulation, mineral and trace element absorption and host defence against infection." (PMID 32059637, 2020).
CSN2 also shares sentences with these, for which no sentence is quoted: colorectal adenoma (1 paper); cystic tumors (1); food allergy (1); hepatocellular carcinoma (1); lactose intolerance (1).